CD44 (CD44 molecule (IN blood group))
Diseases named in the same sentence as CD44 in open-access papers (continued):
Sharing a sentence is not in itself a finding about the gene and the disease.
lymph node metastasis (continued). "Since tumors expressing CD44 were significantly more likely to be lymph node metastasis than CD44-negative tumors, the joint effects of CD44 status and lymph node metastasis on survival were assessed by Kaplan–Meier analysis, stratifying for CD44 status (positive vs." (PMID 26666511, 2015). "In addition, we found CD44 expression was significantly associated with TNM stage, lymph node metastasis and distant metastasis." (PMID 26408312, 2015). "More than 80 % of tumors with lymph node metastasis showed overexpression of CD44." (PMID 26666511, 2015). "There was a strong correlation between CD44 expression and lymph node metastasis (P = 0.002)." (PMID 26666511, 2015). "Seven of 8 samples from lymph node metastases analyzed had the CD44+/CD24- phenotype." (PMID 24119896, 2013). "Therefore, decreased CD44 expression in OSCC tissues may serve as an indicator of high metastatic potential and be associated with lymph node metastasis and poor prognosis." (PMID 41303421, 2025). "Thus, upregulation of CD44 expression may also play a role in lymph node metastasis and its increased aggressiveness in the endometrium." (PMID 41013561, 2025). "CD44 expression may be correlated with tumor grade, advanced T stage and lymph node metastasis." (PMID 32434417, 2020). "In total, there were eighteen L‐R pairs decreased in NPC patients with lymph node metastasis, and the communication probability of five pairs including MIF‐(CD74 + CXCR4), MIF‐(CD74 + CD44), LGALS9‐CD45, IL16‐CD4 and CCL19‐CCR7 were increased in NPC_LNM." (PMID 39392128, 2024). "Next, a comparative analysis of the cell cycle in the primary tumor and lymph node metastasis showed that the two CSC-like clusters (HMGA1-high and CD44/MYC-high) had an increased cell division index in lymph node metastasis." (PMID 35611554, 2022). "In contrast, Soave and collaborators tested CD44 combined with CD24 in adenocarcinomas of the salivary glands, and found a strong correlation with tumour size and lymph node metastasis." (PMID 33009929, 2021). "Having in the mind that a key event in the progression of BC is the development of lymph node metastases, it is very important to determine prognostic benefit of standard and new molecular markers (ER, HER2, EZH2, CD44) on the occurrence of metastatic disease." (PMID 33235571, 2020). "Other commonly used biomarkers, such as Sox2, CD44, were also found to be correlated with clinical characteristics of HNC, such as staging, tumor size and lymph node metastasis." (PMID 32357409, 2020). "The expression of CD44 was also positively correlated with the TNM stage (p = 0.008), vessel invasion, and lymph node metastasis (p = 0.043)." (PMID 26769843, 2016). "The expression of CD44, MMP7 and β-catenin showed a positive correlation with TNM stage, distant metastasis and lymph node metastasis (P < 0.05)." (PMID 26408312, 2015). "The majority of the CD44+/CD24+ cases (66,6%) were classified as T3/T4 and the rate of positive lymph node metastasis was higher than the expected (35.7%)." (PMID 23419168, 2013). "P-LVD was significantly correlated with lymph node metastasis, LVSI, tumor stage and CD44 expression in endometrial carcinoma (P < 0.05)." (PMID 20374665, 2010). "The findings were analyzed in combination with data regarding lymph node metastasis, lymph vascular space invasion (LVSI), CD44 expression, and other clinicopathological parameters." (PMID 20374665, 2010). "P-LVD was significantly correlated with lymph node metastases, lymph vascular space invasion (LVSI), tumor stage, and CD44 expression in endometrial carcinoma samples." (PMID 20374665, 2010). "In this study, 76.3% of the cases showing a high expression of CD44 had lymph node metastases, and 93.4% of cases showing a low expression of CD44 had no lymph node metastases." (PMID 36756017, 2023). "Lymph node metastasis cases showed more negative CD44 expression (59.5%) than lymph nodes without metastasis (20%)." (PMID 37461792, 2023).
lymph node metastasis (continued). "Lymph node metastasis cases showed more negative CD44 expression (59.5%) and the same was noted in patients without distant metastasis, that is in 61% of the subjects." (PMID 37461792, 2023). "Among 15 subjects without lymph node metastasis, CD44-positive expression was seen in 12 patients which was around 80% which implies that there was greater expression in patients without lymph node metastasis." (PMID 37461792, 2023). "Univariate analysis using logistic regression demonstrated that CD44 high expression was not correlated with age, gender, tumor grade, T stage, lymph node metastasis, and distal metastasis (all P values > 0.05)." (PMID 32434417, 2020). "Twenty cases (33%) lacked lymph node metastases; 18(35%) cases showed CD44 expression." (PMID 40881916, 2025). "Of the 25 CD44-positive cases, 14 (56%) were considered H-IRS, and, in 7 of these cases, there was locoregional lymph node metastases at the time of diagnosis; 11 (44%) were considered L-IRS, and, in 5 of these cases, there was locoregional lymph node metastases at the time of diagnosis." (PMID 37173926, 2023). "Additionally, the authors showed that CD44 expression was higher in patients with advanced diseases represented by lymph node involvement (N1) compared to that in individuals without lymph node metastases (N0)." (PMID 28659655, 2017). "At the same time, the rate of lymph-node metastases in patients with the CD45-EpCAM+CD44+CD24-N-cadherin- CTC subset was equal to 75% (3/4); in the absence of such a CTC subset, lymph-node metastases were developed in 14.3% (2/14) of patients (p = 0.044)." (PMID 32316333, 2020). "Expression of CD44 and CD47 correlated with patient surgical stage, chemotherapy resistance and prognosis (all p < 0.05), and expression of c-met correlated with chemotherapy resistance and prognosis (all p < 0.05), but did not correlate with lymph node metastasis (all p > 0.05)." (PMID 25658794, 2015).
non-small cell lung carcinoma (59 papers, 2010 to 2025). A group of at least three distinct histological types of lung cancer, including non-small cell squamous cell carcinoma, adenocarcinoma, and large cell carcinoma. "In this study, we aimed to evaluate the association of single nucleotide polymorphisms (SNPs) in the OPN and CD44 genes with clinical outcomes in 307 non-small cell lung cancer (NSCLC) patients treated with radiotherapy or chemoradiotherapy." (PMID 38067149, 2023). "Subsequent immune checkpoint analysis revealed that the high risk group had increased expression of CD44, a stemness marker of non-small cell lung cancer, and activation of CD44 related pathways promoted squamous cell lung cancer resistance to FGFR1 inhibition." (PMID 36814485, 2023). "Based on the results of these inquiries, it has been shown that non-small cell lung cancer cells have a predilection for internalizing nanoparticles that are specifically designed to target CD44." (PMID 41367861, 2025). "Serglycin, another CD44 ligand, facilitates tumorigenesis through its glycosaminoglycans-mediated binding, regulating CD44 expression via β-catenin signaling and promoting migration in non-small cell lung cancer." (PMID 40363706, 2025). "The binding of SRGN to CD44 induces cytoskeletal reorganization and facilitates Src-mediated turnover of adhesion to the lesions, thereby increasing cell migration in non-small cell lung cancer." (PMID 39816677, 2025). "DGCR5 acts as a key regulator of CSCs in non-small-cell carcinoma by modulating the miR-330-5p/CD44 axis." (PMID 41008534, 2025). "miR-125b, a miRNA known to promote M1 macrophage polarization, was delivered using CD44-targeted hyaluronic acid-poly(ethylenimine) (HA-PEI) NPs in a non-small cell lung cancer (NSCLC) model." (PMID 41376820, 2025). "ICG-PTX nanoparticles are being used to guide drug delivery targeting CD44-positive non-small cell lung cancer (NSCLC)." (PMID 37576984, 2023). "In non-small cell lung cancer, where CD44 was overexpressed, CD44s and MMP-2 co-expression was significantly associated with the lymph node metastasis, higher tumour TNM staging and poor patient prognosis." (PMID 34944493, 2021). "TGFβ also induced proteolytic cleavage of CD44 in another non-small-cell lung cancer cell line, H1299, in a time course- and concentration-dependent manner." (PMID 33804427, 2021). "We have previously shown that SRGN in non-small cell lung cancer (NSCLC) promotes malignant phenotypes in a CD44-dependent manner and increased expression of SRGN predicts poor prognosis of primary lung adenocarcinomas." (PMID 31898491, 2020). "CD44+ non-small cell lung cancer (NSCLC) cells were shown to specifically form spheroids and induce tumor initiation via induction of NANOG, OCT4, and SOX2 overexpression." (PMID 31137841, 2019). "CD44 rs187115 is also correlated with bone metastasis and tumor stage in non small cell lung cancer (NSCLC) patients." (PMID 27323782, 2016). "In non-small cell lung cancer, CD44+-sorted cells with stem cell-like properties were found to be more resistant to cisplatin than CD44- cells." (PMID 24884875, 2014). "ABCC2 expression is upregulated in non small cell lung cancer cells (H322) overexpressing CD44, which are more resistant to cisplatin when cultured on a HA matrix." (PMID 24124770, 2013). "AP-1 has an increased activity in small cell and non-small cell lung carcinomas, which lead to an increase in CD44 expression." (PMID 23226410, 2012). "This multifarious CD44-targeted nanocarrier has the potential to be useful in therapeutic settings, as shown by the case study, which indicates that it inhibits the development of tumors in preclinical models of non-small cell lung cancer." (PMID 41367861, 2025).
non-small cell lung carcinoma (continued). "The high expression of both CD44 and CD90 was associated with significantly reduced relapse-free survival in patients with non-small cell lung cancer, suggesting that CD44+CD90+ cells may have stronger CSC properties." (PMID 36902429, 2023). "In addition, sorting non-small cell lung cancer (NSCLC) cells using the cancer stem cell marker CD44 revealed elevated GTP-RALA levels in the CD44high putative stem cell population compared to CD44low populations." (PMID 35626682, 2022). "DGCR5 was upregulated in lung adenocarcinoma tissues and promoted cancer progression through inhibiting miR-22-3p, and the same team concluded that DGCR5 contributed to the cancer stem cell–like properties in non-small cell lung cancer through interacting with miR-330-5p/CD44." (PMID 34322486, 2021). "Hence, a triple-positive marker, EPCAM+/CD166+/CD44+, has recently been described in the human non-small cell lung cancer cell line." (PMID 32391123, 2020). "Differential edges of CD44 variant, NM_001001390 and CEACAM variant, NM_000610 with EGFR-NM_201283 clues their collective role in cancer and are also reported to be critical in non-small cell lung cancers." (PMID 25034693, 2014). "CD44 variant, NM_001001390 and CEACAM1 variant, NM_000610 are found to be linked to NM_201283 of EGFR, in cancer samples and are also in reported to be critical in non-small cell lung cancers." (PMID 25034693, 2014). "A cluster of differentiation 44 (CD44), which is a non-kinase cell-surface transmembrane glycoprotein and a marker for cancer stem cells, has been reported to be associated with poor prognosis in non-small-cell lung cancer (NSCLC)." (PMID 35563313, 2022). "Notably, CD44 has been described as co-expressed with hnRNP B1 in non-small cell lung cancers." (PMID 29547514, 2018). "Furthermore, CD44 increased chemoresistance in non-small cell lung cancer by upregulation of ABCC2." (PMID 29371972, 2017). "CD44 has been also identified as a CSC marker/regulator in many types of cancers, such as in breast, colorectal and non-small-cell lung cancer (NSCLC), among others." (PMID 35326607, 2022). "(B) CD44 and NUMB exon peak plots relative to the AS analysis of the RNAseq data obtained from a previous ESRP1-KD study in human non-small cell lung cancer cells (H358) and from our own HCT116 and SW480 EpCAMhi/lo analysis." (PMID 36346211, 2022). "The expression of CD44, which is a cell surface receptor for OPN, is down-regulated in non-small cell lung cancer (NSCLC) tissue when compared with paired normal lung tissue." (PMID 34209679, 2021). "In non-small-cell lung cancer, EGCG, enhanced the levels of mir-485-5p, suppressing the levels of two oncogenic targets, CD44 and the nuclear receptor RXRα, both effects contributing to the decrease in CSC-like properties." (PMID 34884848, 2021). "In non-small cell lung cancer (NSCLC) cells, for example, CD133 and CD44 are CSC markers that confer drug resistance and stem cell-like properties." (PMID 27285762, 2016). "It has been shown that CD44+, and not CD44-, tumor cells sorted out from the primary mouse xenografts of non-small cell lung cancer (H1299) tumors exhibited shorter tumor latency in the subsequent tumor formations." (PMID 33540535, 2021). "Immunohistochemical analysis of 141 resected non-small cell lung cancers showed tumor cell expression of CD44 in 50.4% of tumors while no CD34, and CD133 expression was observed in tumor cells." (PMID 21124918, 2010). "Moreover, in A549GSC and H1650GSC cells, treatment with atRA was shown to dramatically lower the IC50 values for gefitinib, an ATP-competitive EGFR tyrosine kinase inhibitor used in non-small cells lung cancer (NSCLC) treatment, and the high expression of ALDH 1 family member A1 (ALDH1A1) and CD44." (PMID 36902427, 2023).
lung adenocarcinoma (57 papers, 2011 to 2026). A carcinoma that arises from the lung and is characterized by the presence of malignant glandular epithelial cells. "Further, CD44 activation of PD-L1 was shown to be associated with immune infiltration, as depletion of CD44 in lung adenocarcinoma cells was linked with B cell, CD4+ T cell, neutrophil and dendritic cell infiltration." (PMID 35269569, 2022). "Absence of the p41 CD74 isoform seems to prevent associations between CD74 and CD44 in human lung adenocarcinoma-derived cells." (PMID 36142162, 2022). "CD44 expression for example was associated with low pathologic stage in lung adenocarcinoma, while expression of the stem cell transcription factor Nanog correlated with high histologic grade that was associated with a poor prognosis." (PMID 32830458, 2021). "Subsequently, we investigated the relationships between CD44 polymorphisms and clinicopathological characteristics of male patients with lung adenocarcinoma (n = 126)." (PMID 32344833, 2020). "We revealed that these patients with the CD44 rs11821102-variant genotypes (GA + AA) exhibited a higher risk of lung adenocarcinoma with the development of the EGFR L858R mutation." (PMID 32344833, 2020). "Here we demonstrated that male individuals carrying at least one A allele in CD44 rs11821102 had a higher risk of lung adenocarcinoma harboring the EGFR L858R mutation than those carrying homozygous GG alleles." (PMID 32344833, 2020). "We assessed CD44 expression and its association with PD-L1 in lung adenocarcinoma, using Tumor Immune Estimation Resource (TIMER), which was further validated in our patient cohort." (PMID 33372595, 2020). "The present results suggest that CD44 rs11821102 G/A polymorphism is a potential candidate target for the prediction of lung adenocarcinoma with the EGFR L858R mutation in male patients." (PMID 32344833, 2020). "The present data showed that sexual dimorphism was observed in the association between CD44 polymorphisms and the susceptibility of lung adenocarcinoma." (PMID 32344833, 2020). "Since the association between CD44 and PD-L1 was confirmed in lung adenocarcinoma patients, we then tested the landscape of immune cells in lung adenocarcinoma patients using GSE103584." (PMID 33372595, 2020). "In the present study, we demonstrated the clinical relevance of CD44 polymorphisms in male patients with lung adenocarcinoma." (PMID 32344833, 2020). "The data suggested that men carrying at least one A allele in CD44 rs11821102 had a higher risk of developing lung adenocarcinoma harboring the EGFR L858R mutation than those carrying homozygous GG alleles." (PMID 32344833, 2020). "We have first conducted the study to ascertain the association between CD44 and PD-L1 in lung adenocarcinoma." (PMID 33372595, 2020). "Our data enhance understanding of the involvement of CD44 SNPs in cancer susceptibility and clinicopathological characteristics in male patients with lung adenocarcinoma." (PMID 32344833, 2020). "Increased CD44 expression was described to be associated with a poor outcome in lung adenocarcinoma patients and tumor progression." (PMID 26807202, 2015). "For CD44, our previous study has shown a contradictory association with well-differentiated AD and a longer patient survival in lung adenocarcinomas." (PMID 24091605, 2013). "In contrast, reports indicate that CD44+ may be associated with immune cell responses and PD-L1 expression in lung adenocarcinoma." (PMID 41305000, 2025). "However, the role of CD44 polymorphisms in the clinicopathological characteristics of lung adenocarcinoma is still unclear." (PMID 32344833, 2020). "Since our study only explores the Taiwanese group, it needs to further study whether the CD44 gene polymorphism is as a risk factor for the susceptibility of male lung adenocarcinoma, particularly those with wild-type EGFR, in other races." (PMID 32344833, 2020).